S100B (S100 calcium binding protein B)
Diseases named in the same sentence as S100B in open-access papers (continued):
Sharing a sentence is not in itself a finding about the gene and the disease.
diabetes (continued). "Diabetes and MI induction each alone induced expression of S100B and RAGE in the heart; but in the post-MI myocardium, only in diabetic mice, the expression of S100B was attenuated." (PMID 32211423, 2020). "Chloe Stenkamp16 and his colleague reported that obesity and diabetes progressed in high-fat diet mice did not alter S100β, Sox10 and GFAP expression in myenteric of EGC." (PMID 30140011, 2018). "The EGC in the myenteric plexus of stomach were decreased in 56–63-day diabetes rats but not in 7–14-day diabetes rats, and, compared with that in 7–14-day control rats, the expression of S100B in 56–63-day control rats also decreased." (PMID 24860604, 2014). "The absence of maternal (e.g., CNS disorders), obstetric (e.g., diabetes, hypertension, placental insufficiency), or fetal (e.g., acute/chronic hypoxia) complications—conditions known to elevate S100β—may have influenced our results." (PMID 40870426, 2025). "Moreover, it is known that metabolic disorders characterized by hyperglycemia, dyslipidemia, hypertension, chronic inflammation, or insulin resistance, especially in diabetes (regardless of type) and obesity, often show higher S100B levels than in the control group." (PMID 39519343, 2024). "In this respect, the observed relationship linking S100B levels to insulin resistance in psychiatric patients may be intriguing, although experimental data correlating S100B to the putative connection between diabetes and AD dementia at present are lacking, thus deserving further investigation." (PMID 38255850, 2024). "We did not observe differences in the relative amount of HMGB1, S100B, S100A6 and SOD1 proteins in SN harvested from diabetic and control mice at six months after diabetes induction in our experiment (P ≥ 0.05)." (PMID 37462767, 2023). "Despite these results, no S100-β peptide epitopes targeted by CD8+ cytotoxic T lymphocytes (CTLs) in T1D patients have been identified, nor has their potential effectiveness in preventing diabetes development been reported." (PMID 30817223, 2019). "Our finding showed that the S100B expression significantly increased after SGES-60 mins and SGES-7 days in 56–63-day diabetes rats but not in 7–14-day diabetes; the effect of SGES on gastric emptying may be related to active EGC." (PMID 24860604, 2014).
ischemia (33 papers, 2008 to 2026). A hypoperfusion of the BLOOD through an organ or tissue caused by a PATHOLOGIC CONSTRICTION or obstruction of its BLOOD VESSELS, or an absence of BLOOD CIRCULATION. "Three studies evaluated the association between serum S100B level and neurologic deterioration attributed to ischemia." (PMID 27007976, 2016). "It has also been hypothesized that in the context of infarcted brain tissue, astroglia necrosis and membrane instability in the penumbra region around the ischemia cause cytosolic S100β to leak into the extracellular space, leading to the raising serum S100β concentrations." (PMID 39970158, 2025). "Higher postoperative S100B is correlated with lower cortisol, measured at the same time point, which probably could be explained by the lower blood pressure associated with lower stress and with the consequent silent ischemia." (PMID 34884182, 2021). "In terms of the number of S100b+ cells (Schwann cells), maximum values were achieved 28 days after modeling ischemia in the groups with cell-mediated delivery of the genetic constructs UCBC Ad5-Vegf + Ad5-Ang and UCBC Ad5-Vegf + Ad5-Ang + Ad5-Gdnf." (PMID 39194724, 2024). "At 42 days after modeling ischemia, the highest number of S100b+ cells was registered in the UCBC Ad5-Vegf + Ad5-Ang group, where this index was 2.4 times higher (p < 0.5) in comparison with the NaCl control group." (PMID 39194724, 2024). "There is a correlation between serum S100β protein level and infarct volume on Days 1–4 of ischemia, which can predict the severity of brain injury and survival and provide value for neurologic examination and neuroradiologic findings." (PMID 39669376, 2024). "The S100β protein leakage from astrocytes starts after 4 h from the ischemia onset and depends from depth of the cerebral blood flow reduction and tissue destruction." (PMID 31701356, 2020). "The correlation between the S100β protein serum level and the infarct volume has been revealed between the first and the fourth day of ischemia." (PMID 31701356, 2020). "A single measurement of S100β protein in serum between 12 and 24 h after ischemia onset has a predictive value and can be a valuable confirmation of the results assessed on the basis of neurological examination and neuroradiological studies." (PMID 31701356, 2020). "In detail, the area of clear ischemia-related affection was demarked by a decrease of the immunosignal for S100b and Gfap and—to a much lesser degree—also Glul, accompanied with a degradation of the cellular formations in this region." (PMID 31089963, 2019). "S100B elevation also reflected secondary brain deterioration due to vasospasm induced ischemia, brain edema, and hydrocephalus." (PMID 30011792, 2018). "By following the dynamics of S-100β and antioxidant capacity, our study adds to the knowledge of when the spinal cord is exposed to ischemia after TEVAR." (PMID 28740858, 2017). "Thereby, anti-S100β was found to visualize predominantly astroglial somata in both the ischemia-affected and the control region." (PMID 28445478, 2017). "It has been suggested that the increased S100B in aging is related to a lifetime of proinflammatory events, including ischemia, trauma, and infections." (PMID 20827311, 2010). "This discrepancy may reflect a delayed normalisation of S100B following acute ischemia or indicate that cognitive recovery may be driven more by reduced inflammation than by immediate neuronal repair." (PMID 41281269, 2025). "Additionally, damps such as S100B and ATP are released into the extracellular space during ischemia and in large quantities in the early phase of ischemia." (PMID 37062906, 2023). "Interestingly, increased levels of S100B have been reported in the brain during ischemia, and S100B levels in umbilical cord blood have been suggested to be a potential biomarker of hypoxic-ischemic encephalopathy in asphyxiated newborns." (PMID 34360919, 2021).
ischemia (continued). "Indeed, Vujosevic and co-workers administered S100B intravitreal injections that induced ischemia and glaucoma-like symptoms with early optic nerve axon degeneration, followed by retinal cell body damage." (PMID 33670473, 2021). "Indeed, brain injury following trauma or peri-traumatic ischemia increases the concentration of specific biomarkers, such as S100β protein, neuronal-specific enolase (NSE), ubiquitin C-terminal hydrolase-L1 (UCH-L1), and glial fibrillary acidic protein (GFAP)." (PMID 31547411, 2019). "Interestingly, serum S100B levels have been shown to correlate not only with ischemia, rather with the size of ischemic lesion also, irrespective of treatment or CVS association." (PMID 30011792, 2018). "In TBI patients, S100B has been shown to correlate to the extent of hypodense lesions at hospital admission, perinatal asphyxia as well as subsequent ischemic development, indicating that if ischemia is added to brain injury, it would lead to an additional increase of S100B." (PMID 27014178, 2016). "Although the low number of patients with grade II ischemia as well as the variance in samples led only to a weak correlation between S100B and degree of ischemia in this study, we could confirm S100B in serum as an indicator for cerebral ischemia." (PMID 23509668, 2013). "Moreover, chronic over-expression of human S100B increases brain damage and peri-infarct gliosis after focal ischemia." (PMID 20827311, 2010). "First, the lack of neuroimaging may have precluded the ability to study the association of S-100β with MRI findings of ischemia, rather than relying on the clinical exam alone." (PMID 28740858, 2017). "The study revealed significantly lower serum levels of neuron‐specific enolase and S‐100B in the RIPC group, indicating reduced neuronal injury and improved spinal cord tolerance to ischemia." (PMID 41522823, 2026). "S100b levels are higher at least 48 h after the onset of cerebral ischemia, whereas GFAP levels increase sooner after ischemia onset, making it a more suitable biomarker for early diagnosis." (PMID 40863995, 2025). "Administration of atorvastatin reduced serum S100B levels among high WFNS score patients and reduced the severity and incidence of vasospasms leading to ischemia." (PMID 30011792, 2018). "Given the current hypotheses of the complex mechanisms contributing to delayed cerebral ischemia, there may be other pathways independent of vasospasm which explain the increased serum S100B level and its relationship with ischemia despite its lack of association with radiographic vasospasm." (PMID 27007976, 2016). "CSF glutamate and serum S100B were significantly correlated with ischemic events after SAH; however, NSE did not correlate neither with ischemia nor with vasospasm." (PMID 23509668, 2013). "In order to investigate the different patterns of astroglial immunoreaction in more detail, immunolabeling of S100β as a further marker for astrocytes were combined with GFAP- and STL-staining in the ischemia-affected neocortex compared to the contralateral, non-affected hemisphere." (PMID 28445478, 2017). "Serum S100B, but not NSE, is a suitable marker for ischemia." (PMID 23509668, 2013).
Obesity (30 papers, 2010 to 2025). Accumulation of substantial excess body fat. "Elevated circulating levels of S100B have been associated with obesity, insulin resistance, and neurodegeneration in humans." (PMID 41343575, 2025). "The S100B, which is expressed in adipose tissue, has been associated with the pathophysiology of obesity-promoting macrophage-based inflammation." (PMID 37960185, 2023). "Some S100 members (e.g., S100A4, S100A8/A9, S100A12 and S100B) have also been suggested to represent potential biomarkers of NAFLD-associated disorders such as obesity, type 2 diabetes, IR and inflammation." (PMID 36232334, 2022). "Certain S100 proteins, namely S100A4, S100A8/S100A9 heterodimer, and S100B, have been implicated in the pathophysiology of obesity-promoting macrophage-based inflammation via toll-like receptor 4 and/or receptor for advanced glycation end-products ligation." (PMID 35328627, 2022). "The S100 protein family members, S100A4, S100A8/A9 heterodimer, and S100B have all been implicated in the pathophysiology of obesity-associated inflammation via their interaction with RAGE." (PMID 34204735, 2021). "As compared to risk-free carriers, active beige adipocytes with FTO obesity-risk genotype had lower expression of these thermogenic genes and also that of the neurotrophic factor S100b, which was postulated to stimulate sympathetic axon growth and to play an important role in BAT innervation." (PMID 37416800, 2023). "Decreased expression of S100b in abdominal SC adipocytes with FTO obesity-risk carriers, however, might partially contribute to lower thermogenic capacity in abdominal SC WAT even when the adipocytes are activated for heat production." (PMID 37416800, 2023). "For example, small vessel ischemic disease associated with obesity is a source of serum S100B." (PMID 20844757, 2010). "In fact, it has been postulated that BDNF might perform functions related to satiety induction and increased energy expenditure in obesity, while S100B seems to be associated with inflammatory markers, and positively associated with body mass index (BMI), and with serum leptin levels." (PMID 34591410, 2021). "This dual regulation reconciles our findings with previous reports that serum S100B is elevated in obesity and neuroinflammation." (PMID 41343575, 2025). "In our study, BP patients with obesity and MS had a higher serum level of S100B in exacerbation than BP patients with normal BMI, and without MS." (PMID 37960185, 2023). "Our results show, on the one hand, the relationship between the S100B levels and obesity and MS, and on the other hand, with the mental state of patients." (PMID 37960185, 2023). "In studies conducted on mice, plasma and white adipose tissue S100B levels were increased by diet-induced obesity." (PMID 37960185, 2023). "In this study, we targeted S100B-the downstream of YAP/TAZ by adipocyte-specific promoter-driven expression in eWAT, which improved obesity and associated metabolic disorders." (PMID 37925548, 2023). "Recent publications suggest the involvement of S100B in obesity and diabetes mechanisms, possibly by participating in the inflammatory processes." (PMID 37960185, 2023). "In fact, an increase in adipose S100b gene expression in WAT is observed during obesity, which, in common with markers of adipose tissue inflammation, can be reversed following weight loss." (PMID 32486507, 2020). "The contrasting expression patterns of Clsnt3β and S100b in BAT in the context of obesity is particularly intriguing." (PMID 33101212, 2020). "The purpose of this study was to investigate plasma levels of sRAGE and the RAGE ligand S100B in individuals with metabolic disturbances such as obesity, impaired fasting glucose, elevated amylin, and T2DM comorbid with AD." (PMID 29681765, 2018). "S100B is secreted by adipocytes and is involved in the pathogenesis of obesity as shown in vitro and in vivo." (PMID 26500502, 2015).
Obesity (continued). "In conclusion, S100B blood levels are directly related to BMI across an extensive range of nutritional states spanning from starvation to extreme obesity." (PMID 20631894, 2010). "Elevated endogenous levels of S100B have been observed in patients with obesity and insulin resistance, where they may contribute to systemic low-grade inflammation and metabolic dysfunction." (PMID 40723919, 2025). "In this respect, S100B might contribute to low-grade inflammation in adipose tissue and promote the development of obesity-related complications." (PMID 38255850, 2024). "Also, in a human study, serum levels of S100B positively correlate with BMI; S100B levels in obesity were significantly higher than in overweight and normal weight subjects." (PMID 37960185, 2023). "Therefore, this trial mainly aimed to examine the effect of thylakoid intervention on oxidative level, LPS as marker of gut permeability, and BDNF and S100B levels as neurotrophic factors in PCOS women with obesity who were on a low-calorie diet." (PMID 37968684, 2023). "All together, these data indicate that ectopically expressing S100B in vWAT by AAV could be an effective and safe means to treat obesity and associated metabolic disorders." (PMID 37925548, 2023). "Since BDNF and S100B protein are involved in both FM and obesity, it is reasonable to hypothesize an interplay among these biomarkers as far as brain plasticity is concerned, in the modulation of eating behavior in FM." (PMID 34591410, 2021). "Indeed, an opposite trend was observed for S100b (induced by obesity in mouse BAT), and for Ucp1, at this stage upon HFD feeding." (PMID 33101212, 2020). "Importantly, S100B is overexpressed in the brain of AD patients and elevated in serum of persons with obesity." (PMID 29681765, 2018). "HMGB1 released by necrotic adipocytes interacts with RAGE, inducing pro-inflammatory cytokines and ROS;S100A4, S100A8/A9, and S100B induce inflammation, interacting with RAGE;AGE accumulation in adipose tissue may contribute to obesity-associated insulin resistance." (PMID 34204735, 2021). "In particular, we address the question as to whether circulating levels of pro-inflammatory markers, such as leptin and IL-6, or markers of cerebral plasticity, such as BDND and S100B, are related to the temporal sensitivity in obesity, through a cross-sectional study." (PMID 31664059, 2019). "DAMP proteins HMGB1 and S100B were identified as potential targets for assessing pro-inflammatory signaling in hibernating ground squirrels because both are highly expressed in adipose tissues, and are upregulated in diet-induced obesity mice models and following high fat diets in mice." (PMID 29888131, 2018). "Future studies are needed to determine if the increase of S100β and NSE in children with obesity is related to cognitive function." (PMID 41286426, 2025). "Enhanced S100β levels, suggestive of reactive gliosis, have been shown during absence of TLR4 or TLR2 signaling, enteric dysbiosis, diet-induced obesity, impaired mitochondrial respiration, mechanical nerve injury." (PMID 33923250, 2021). "While our findings highlight an interesting regulation of Clstn3β in conditions associated with BAT dysfunction, this calls for further investigation about the complex interplay between Clstn3β, S100b and Ucp1 in BAT in the context of obesity." (PMID 33101212, 2020). "Therefore, it is not clear whether obesity itself or obesity-associated comorbidities contribute to a rise in serum S100B in the previous studies." (PMID 20844757, 2010). "In our study, obesity did not significantly affect S100B serum levels while in diabetic patients, S100B serum levels were significantly higher than in nondiabetic ones (P = .013)." (PMID 20671945, 2010).
Obesity (continued). "The two markers of cerebral plasticity (BDNF and S100B) were not significant predictors of the behavior in our participants, corroborating our hypothesis about the relationship between inflammatory state and poorer temporal sensitivity in obesity." (PMID 31664059, 2019). "Thus, they concluded that “an increase in fat mass might not in isolation be a major contributor to elevated S100B levels”89, suggesting the possible contribution of other obesity-related diseases in the expression of the protein." (PMID 31664059, 2019).